MCUB (mitochondrial calcium uniporter dominant negative subunit beta)
Description:
Negative regulator of the mitochondrial calcium uniporter (MCU), a channel that mediates calcium uptake into the mitochondrial matrix. MCUB is required to limit mitochondrial calcium overload during stress. Acts as a dominant-negative regulator that displaces MCU from the functional uniplex complex and thereby decreases the association of calcium sensors MICU1 and MICU2, preventing channel gating. Mitochondrial calcium homeostasis plays key roles in mitochondrial metabolism. Acts as an important regulator of mitochondrial metabolism in response to stress in muscle cells: induced in response to fasting, leading to restrict mitochondrial calcium uptake, resulting in reprogramming of mitochondria toward fatty acid oxidation preference (By similarity). Acts as a regulator of macrophage polarization during skeletal muscle regeneration: inhibition of mitochondrial calcium uptake drives differentiation of macrophages with anti-inflammatory profile, promoting the differentiation and fusion of satellite cells (By similarity).
Synonyms: CCDC109B; FLJ20647
Tractability: Antibody: UniProt predicts a signal peptide or a membrane-spanning region. PROTAC: ubiquitination databases record sites on it.
Gene: Protein-coding gene on chromosome 4 (109,560,209 to 109,688,719, forward strand). Ensembl gene ENSG00000005059.
Subcellular location: Mitochondrion inner membrane
Subcellular location (Human Protein Atlas): Mitochondria; Cytosol
Pathways (Reactome):
Transport of small molecules: Mitochondrial calcium ion transport; Processing of SMDT1
Gene Ontology:
Molecular function: calcium channel inhibitor activity; protein binding; monoatomic ion channel activity
Biological process: negative regulation of calcium import into the mitochondrion; calcium import into the mitochondrion; mitochondrial calcium ion homeostasis; mitochondrial calcium ion transmembrane transport; positive regulation of skeletal muscle satellite cell differentiation; regulation of macrophage activation; skeletal muscle tissue regeneration
Cellular component: mitochondrial inner membrane; mitochondrion; uniplex complex; calcium channel complex; membrane
Genetic constraint (gnomAD): Loss-of-function variants: 3 observed, 5.04 expected, observed/expected ratio (o/e) 0.6, 90% interval 0.27 to 1.49. That is too few expected variants to judge how well the gene tolerates losing a copy. Missense variants: 62 observed, 72.06 expected, observed/expected ratio (o/e) 0.86, 90% interval 0.7 to 1.06. Synonymous variants: 19 observed, 30.42 expected, observed/expected ratio (o/e) 0.62, 90% interval 0.44 to 0.92.
Homologues: Orthologues: chimpanzee MCUB (98% identical), macaque MCUB (96% identical), dog MCUB (82% identical), pig MCUB (81% identical), mouse Mcub (74% identical), rat Mcub (71% identical), rabbit MCUB (70% identical), tropical clawed frog mcub (51% identical). Paralogues in human: MCU (44% identical).
Diseases named in the same sentence as MCUB in open-access papers:
MCUB is named in the same sentence as 23 diseases in open-access papers, as found by Europe PMC text mining. Sharing a sentence is not in itself a finding about the gene and the disease. The quoted sentences say what the papers report.
glioma (9 papers, 2017 to 2025). A benign or malignant brain and spinal cord tumor that arises from glial cells (astrocytes, oligodendrocytes, ependymal cells). "Aberrant expression of MCUb has been associated with the malignant properties of gliomas." (PMID 36538269, 2023). "The expression levels of MCUb are inversely associated with overall survival in glioma." (PMID 34070562, 2021). "MCUB is involved in facilitating glioma invasion/migration under hypoxic conditions." (PMID 37660060, 2023). "Interestingly, it has been reported that MCUb silencing limits glioma cell proliferation, migration, and invasion, as well as glioma progression in vivo." (PMID 34070562, 2021). "Silencing of MCUB using shRNAs in U87MG and U251 human glioma cell lines inhibited proliferation, migration, and invasion and led to decreased tumor volume and prolonged overall survival in orthotopic tumor models of nude mice." (PMID 36538269, 2023). "Thus, MCUb may be a potential tumor promotor in glioma progression, which is drastically upregulated under hypoxia and could be used as a prognostic marker or targeted as a novel treatment in human glioma." (PMID 36538269, 2023). "Specifically, MCUb was highly expressed in high‐grade gliomas compared to almost no expression in normal brain tissue; further, high MCUb expression correlated with an increased tumor grade." (PMID 36538269, 2023).
breast carcinoma (3 papers, 2016 to 2024). "While this article delves into the mutation of MCU in breast cancer, it's crucial to note that MCUb forms hetero-oligomers with MCU, and expressing MCUB alone in the lipid bilayer hardly facilitates Ca2 + exchange across the artificial membrane." (PMID 38632642, 2024). "Consequently, we speculate that the mutation of MCUb in breast cancer may also involve another assembly protein, EMRE (Essential MCU Regulator), which is indispensable for uniporter function and mediates the interaction between MCU and MICU1." (PMID 38632642, 2024). "Our preliminary analysis suggests that the decreased significance of EMRE in the breast cancer group might be attributed to the competitive binding of MCUb with MCU, yet this remains unclear at present." (PMID 38632642, 2024). "A fourth study correlated mRNA levels of MCU and related proteins (MCUb, MICU1–3, and EMRE) from the TCGA breast cancer dataset with clinical stages demonstrating that MCU expression increases with tumor size and lymph node infiltration, while MCUb expression decreases." (PMID 28740830, 2017).
ischemia (2 papers, 2021 to 2024). A hypoperfusion of the BLOOD through an organ or tissue caused by a PATHOLOGIC CONSTRICTION or obstruction of its BLOOD VESSELS, or an absence of BLOOD CIRCULATION. "Cardiac stressors such as ischemia induce MCUb expression and thereby decrease Ca2+ uptake via incorporation of MCUb in the MCU complex." (PMID 38890208, 2024).
Stroke (2 papers, 2023). Sudden impairment of blood flow to a part of the brain due to occlusion or rupture of an artery to the brain. "The data on the role of MCUb in type 2 diabetic models are controversial, whereas MCUb in the brain is supposed to play neuroprotective roles for strokes and NDs." (PMID 37833898, 2023). "Given the protective function of MCUb in the heart and the detrimental role of mitochondrial Ca2+ overload in neurons, it is logical to predict that MCUb plays neuroprotective roles in stroke and neurodegenerative diseases." (PMID 36760367, 2023).
type 2 diabetes (2 papers, 2023). "Additionally, in type 2 diabetic mouse hearts, MCUb was found to be upregulated." (PMID 36538269, 2023). "Interestingly, the MCUbW245R/V251E mutant was found to interact with MICU1, but similar to the proteomic data (see Section 3.1) WT MCUb did not interact with MICU1 in cardiomyocytes from the type 2 diabetic mouse hearts." (PMID 36538269, 2023).
Arrhythmia (1 paper, 2023). Any cardiac rhythm other than the normal sinus rhythm. "We discuss physiological and pathophysiological information known about MCUb, underscoring implications in cardiac function and arrhythmia as a basis for future therapeutic discovery." (PMID 36538269, 2023).
breast invasive cancer (1 paper, 2021). "MCU, its dominant-negative form MCUb, LETM1, and VDAC, were found to be upregulated in breast invasive cancer." (PMID 33614647, 2021).
Glioblastoma multiforme (1 paper, 2023). "Glioblastoma multiforme (GBM) samples showed high expression of MCUb and hypoxia‐inducible factor 1‐α (HIF1α), a transcriptional regulator typically induced by hypoxia, both localized in areas bordering necrosis." (PMID 36538269, 2023).
Glucose intolerance (1 paper, 2025). Glucose intolerance (GI) can be defined as dysglycemia that comprises both prediabetes and diabetes. "In addition, mice lacking Mcub (Mitochondrial calcium uniporter dominant-negative subunit beta), an inhibitor of MCU-mediated Ca2+ influx in skeletal muscle, exhibited increased pyruvate dehydrogenase activity, reduced fatty acid utilization, glucose intolerance, and increased adiposity." (PMID 40177518, 2025).
cancer (7 papers, 2013 to 2025). A tumor composed of atypical neoplastic, often pleomorphic cells that invade other tissues. "Collectively, MCUb may contribute to cancer progression through the promotion of cell proliferation and migration and may reveal a therapeutic target for clinical intervention in multiple aggressive cancers." (PMID 36538269, 2023). "Most of these studies report that MCUa, MCUb, MICU1-2, and EMRE have important functional relevance in immunity, muscle cell physiology, as well as pathological conditions such as cancer, cardiovascular and neurodegenerative diseases, among others." (PMID 39623165, 2025). "However, mitochondrial Ca2+ signaling dysregulation and alterations in MCUb expression have been observed as secondary characteristics of many human pathologies, ranging from musculoskeletal disease, neurodegenerative disease, cancer, and diabetes to heart disease." (PMID 36538269, 2023). "In most cancers, the signature genes were differentially methylated compared to normal tissue; in particular, genes including as representatives NCOA4, CTSL, MCUB, ANXA5 and ANGPTL2 were usually hypermethylated, while genes including PDE2A and others were usually hypomethylated." (PMID 37660060, 2023).
tumor (7 papers, 2016 to 2025). "In vivo, MCUB knockdown led to reduced tumor growth, enhanced CD8+ T cell infiltration, and improved response to anti-PD-1 therapy." (PMID 41221601, 2025). "TCGA data corroborated that the expression of MCUb in the tumor group exceeded that in the normal group, akin to MCU." (PMID 38632642, 2024). "Specifically, MCU expression was found to increase with tumor progression, while MCUb expression decreased." (PMID 36538269, 2023). "Thus, enhanced mitochondrial Ca2+ uptake due to increased MCU and decreased MCUb expression may promote HIF1α signaling, leading to increased tumor size and lymph node infiltration in breast cancer." (PMID 36538269, 2023). "In particular, while MCU expression increases with tumor progression, the expression of MCUb, the dominant‐negative channel isoform, decreases." (PMID 27138568, 2016).
cardiovascular disease (1 paper, 2025). "Interestingly, while some reports have indicated that elevated MCUB expression exerts protective effects in cardiovascular disease, our results appear to diverge." (PMID 40422231, 2025).
MCUB also shares sentences with these, for which no sentence is quoted: acute lymphoblastic leukemia (2 papers); neurodegenerative disease (2); atherosclerosis (1); Bladder Cancer (1); cardiac arrhythmias (1); cervical cancer (1); gastric cancer (1); infection (1); leukemia (1); malignant glioma (1); Sepsis (1).